NANOG (Nanog homeobox)
Diseases named in the same sentence as NANOG in open-access papers (continued):
Sharing a sentence is not in itself a finding about the gene and the disease.
bladder cancer (10 papers, 2012 to 2024). "The overexpression of NANOG remarkably increased the number and size of the spheres in bladder cancer UMUC3 and T24 cells, thus suggesting that NANOG promotes the self-renewal of bladder cancer cells." (PMID 37627900, 2023). "In bladder cancer, tumor progression is associated with the strong up-regulation of SOX2 and NANOG and the consequent acquisition of cancer stem cell properties." (PMID 38096163, 2023). "In another study, Migata et.al show a relationship between epithelial-mesenchymal transition (EMT) and cancer stemness and a decrease in E-cadherin increased the expression of SOX2 and NANOG in bladder cancer cell lines." (PMID 37298099, 2023). "The downregulation of NANOG decreased bladder cancer cell migration and invasion as well as MMP2 and MMP9 mRNA levels." (PMID 37627900, 2023). "Positive NANOG expression was detected in all the formalin-fixed paraffin-embedded (FFPE) bladder cancer tissues with cytoplasmic, nuclear, and nuclear membrane localizations." (PMID 37627900, 2023). "Bladder cancer patients with a high NANOG and CD44 expression had poorer recurrence-free survival and overall survival rates." (PMID 37627900, 2023). "In bladder cancer T24 and 5637 cells, significantly higher mRNA and protein expression of NANOG and OCT4 were observed after exposure to the highest concentration of mitomycin C (chemotherapy drug)." (PMID 37627900, 2023). "An inverse correlation was found between E-cadherin and NANOG/SOX2 expression in bladder cancer tissues." (PMID 37627900, 2023). "EMT promoted stemness involving the overexpression of SOX2 and NANOG in muscle-invasive bladder cancer clinical samples." (PMID 33911182, 2021). "NANOG was significantly expressed in bladder cancer cell lines and tissues." (PMID 37627900, 2023). "Taken together, these findings suggest that NANOG might be useful as a potential biomarker for the diagnosis and prognosis of bladder cancer as well as for the identification of bladder CSCs." (PMID 37627900, 2023). "PTPN12 depletion (shPTPN12) in the weakly metastatic breast and bladder cancer lines (UMUC3) increased ES-TF expression whereas PTPN12 transduction in 1833 decreased NANOG, MYC, and SOX2 expression." (PMID 38886396, 2024). "A combined NANOG and CD44 expression were identified as independent prognostic biomarkers for recurrence-free survival and overall survival in bladder cancer." (PMID 37627900, 2023). "A panel of CSC-related molecules were tested for their potential to detect bladder cancer, and the combination of CD24, CD49f, and NANOG showed promising sensitivity." (PMID 35565191, 2022). "Then, the expression of previously identified bladder cancer stem cell markers (POU5F1, BMI1, NANOG, SOX2,) was determined by real- time qPCR in the established control NT and αv kd cell lines as well as in GLPG0187 treated cells." (PMID 25247809, 2014). "NANOG and BMI1 protein were highly expressed in the bladder cancer tissues." (PMID 37627900, 2023). "The expression of embryonic stem cell markers (OCT4 and NANOG) was significantly higher in bladder cancer T24 and 5637 cells as compared to the controls after exposure to the highest concentration of mitomycin C, thus indicating that OCT4 and NANOG expression were higher in drug-resistant cells." (PMID 37627900, 2023). "POU5F1 has also been shown to have an important role in bladder cancer stem cells, invasion and migration, however, our data suggest that αv integrin might affect migration through a mechanism independent of POU5F1, for example via NANOG or SOX2." (PMID 25247809, 2014).
esophageal cancer (9 papers, 2016 to 2025). A primary or metastatic malignant neoplasm involving the esophagus. "Although this study is limited by its retrospective design, the large size of our cohort (660 patients) allowed us to provide comprehensive insights into the role of NANOG expression in esophageal cancer." (PMID 37461005, 2023). "Despite these limitations, we provided a comprehensive analysis of the association between CD34, CD133, Nucleostemin, OCT-4, NANOG and CD90 stemness markers and OS of patients affected by esophageal cancer." (PMID 32368307, 2020). "The overexpression of NANOG promotes cisplatin resistance in esophageal cancer, and siRNA-knockdown of NANOG increases sensitivity to cisplatin." (PMID 27225481, 2016). "Moreover, aspirin has been effective in reducing the recruitment of M2 TAMs by targeting CCL2, as well as CSC marker NANOG along with declining their sphere formation ability and the expression of CSC marker genes CD90 and NANOG in esophageal cancer." (PMID 38035101, 2023). "The stem cell markers were detected by qPCR in Eca109 cells, and the results showed that overexpression of RBBP7 upregualted the expressions of esophageal cancer stem cell markers, including SOX2, KLF4, NANOG, and OCT3/4." (PMID 35538026, 2022). "We found that the expression of stem cell biomarkers NANOG, OCT4, SOX2 increased in the PTX-resistant esophageal cancer cells." (PMID 34150636, 2021).
head and neck cancer (9 papers, 2013 to 2025). A primary or metastatic malignant neoplasm affecting the head and neck. "Moreover, low levels of oxidative stress increase OCT4 and NANOG, the stemness-associated key transcription factors in head and neck cancers." (PMID 39518936, 2024). "Another study further exhibited that the levels of hypoxia-induced stemness markers such as Nanog homeobox (NANOG) are attenuated by apigenin in head and neck cancer." (PMID 34575983, 2021). "The epithelial expression of NANOG has been described in head and neck cancers." (PMID 36655039, 2023). "Head and neck cancer cells belonging to the stem cell population are distinguished by the high expression of certain surface proteins (e.g., CD10, CD44, CD133), pluripotency-related transcription factors (SOX2, OCT4, NANOG), and increased activity of aldehyde dehydrogenase (ALDH)." (PMID 37453969, 2023). "As expected, NANOG was not expressed in normal tissue but it was expressed in OSCC, as already reported in many types of human cancers, including head and neck cancer." (PMID 32733958, 2020).
lymph node metastasis (9 papers, 2014 to 2025). "Similarly, SOX2 and NANOG expression were both significantly associated with lymph node metastasis (P < 0.01) and advanced AJCC stage (P = 0.016 and P = 0.031, respectively)." (PMID 40626009, 2025). "High NANOG expression was significantly correlated with high grade, deep myometrial invasion, lymph node metastasis, and high stage with p values (0.009, 0.005, 0.014, and 0.003, respectively)." (PMID 35186145, 2022). "In endometrial carcinoma, high NANOG expression was significantly correlated with high grade, deep myometrial invasion, lymph node metastasis, and high stage with p-values (0.009, 0.005, 0.014, and 0.003, respectively)." (PMID 35186145, 2022). "NANOG protein expression was detected in 250 (72%) cases, more frequently in patients with lymph node metastasis (p = 0.003), and was an independent predictor of better survival in multivariate analysis." (PMID 32635524, 2020). "In this study, we observed that the expression of SOX2, but not OCT4 and NANOG, correlates with poor histological differentiation of endometrial tumors, associates with lymph node metastasis, and predicts a poor survival in patients." (PMID 30510261, 2018). "Moreover, a positive relationship between enhanced NANOG expression and lymph node metastasis of carcinoma was reported." (PMID 26626427, 2015). "As a result, the expressions of NANOG and OCT4 were higher in patients with lymph node metastases than in those without lymph node metastases, suggesting the possibility of NANOG as a malignant prognostic marker." (PMID 36497144, 2022). "In our study, expression of OCT4, SOX2 and NANOG genes was slightly, but not significantly, higher in patients without lymph node metastasis." (PMID 31244283, 2019). "Interestingly, multivariable analyses (MVA) showed independent prognostic value for the pluripotency marker NANOG in PDSs cultured with MCF7 cells (HR, 2.541; 95% CI, 1.108–5.827; p = 0.028) after adjustment for ERα-status, grade, age, tumor size and lymph node metastasis." (PMID 35565301, 2022). "In addition, the impact of NANOG expression was greater in patients with lymph node metastasis than in node-negative patients, as was consistently demonstrated at both mRNA and protein levels using two large independent HNSCC cohorts." (PMID 32635524, 2020). "However, NANOG expression did not correlate with gender, region or T (stage of primary tumor) and N (stage of lymph node metastasis) status (P>0.05)." (PMID 24348816, 2014).
non-small cell lung carcinoma (9 papers, 2013 to 2025). A group of at least three distinct histological types of lung cancer, including non-small cell squamous cell carcinoma, adenocarcinoma, and large cell carcinoma. "CD44+ non-small cell lung cancer (NSCLC) cells were shown to specifically form spheroids and induce tumor initiation via induction of NANOG, OCT4, and SOX2 overexpression." (PMID 31137841, 2019). "Because the phosphorylation of HSP27 facilitates the ubiquitination and proteasomal breakdown of proteins that drive stemness (including NANOG, OCT4, c-Myc, SOX2, and KLF4) in non-small-cell lung cancer (NSCLC) cells, the inactivation of p38 promotes the expression of CSC characteristics." (PMID 41369386, 2025). "In contrast, P38γ and P38δ activation may suppress CSCs development in non-small-cell lung cancer (NSCLC) through promotion of the ubiquitin-mediated degradation of SOX2, OCT4, NANOG, KLF4 and MYC transcription factors that normally contribute to the acquisition of cancer stem cell characteristics." (PMID 35409206, 2022).
triple-negative breast carcinoma (9 papers, 2016 to 2025). An invasive breast carcinoma which is negative for expression of estrogen receptor (ER), progesterone receptor (PR), and human epidermal growth factor receptor 2 (HER2). "On this line, another study reported that Cx26 drives self-renewal in triple-negative breast cancer by interacting with focal adhesion kinase and NANOG, indicating a role in targeting and compromising cancer stem cell maintenance." (PMID 33837873, 2021). "Further work in triple-negative breast cancer (TNBC) revealed that Cx26 is capable of interacting with NANOG and focal adhesion kinase (FAK) to drive tumor progression and CSC self-renewal." (PMID 30622930, 2018). "In addition, it would be important to identify common fragile nodes of vimentin, NANOG and CD49f signalling in a more integrated manner in order to evaluate their interest as markers and or new therapeutic targets in triple negative breast cancer." (PMID 34203746, 2021). "Moreover, KDM5B inhibited the expression of pluripotency genes, SOX2 and NANOG, and decreased the stem cell population in triple-negative breast cancer cell lines (TNBC)." (PMID 31776402, 2019). "Likewise, in triple-negative breast cancer, it was found that Cx26 expression was higher in CSCs, and promotes self-renewal by forming a signaling complex with NANOG, a pluripotency transcription factor, and focal adhesion complex." (PMID 30622930, 2018). "A study on triple-negative breast cancer (TNBC) also supports this mechanism: it found that THOC2, dependent on THOC5, facilitates the export of SOX2 and NANOG transcripts, thereby enhancing stemness features and radioresistance." (PMID 40901498, 2025).
endometriosis (8 papers, 2014 to 2024). The growth of functional endometrial tissue in anatomic sites outside the uterine body. "The role of multiple other stem cell markers has been explored, such as SOX2 and NANOG in endometriosis." (PMID 39684461, 2024). "Our findings are in accordance with other endometriosis literature identifying downstream LIF targets NANOG, OCT-3/4, and SOX2 to be elevated in ectopic lesions compared to control endometrium." (PMID 37033980, 2023). "The genes with increased expression (KRT18, KRT19, VIM, and NANOG) were then used in subsequent analyses as “endometriosis confirmatory genes”." (PMID 31717910, 2019). "A larger sample size and the functional research of SOX2 and NANOG in pathogenesis of endometriosis is anticipated in our further study." (PMID 24884521, 2014). "The transcription pluripotency factors SOX2 and NANOG were overexpression in ovarian endometriosis, their role in pathogenesis of endometriosis should be further studied." (PMID 24884521, 2014). "Comparison of SSEA1+ sorted epithelial cells from women with endometriosis and healthy fertile control women (n = 8/group), showed a significant up-regulation of two pluripotency genes NANOG (P = 0.007) and OCT4 (P = 0.05), although the abundance of OCT4 was extremely low." (PMID 30496412, 2019). "Thus, further investigation is required to confirm whether the upregulation of NANOG is due specifically to LIF signaling or other mediators in endometriosis." (PMID 37033980, 2023). "In parallel with the predecidua changes, various CEC types isolated from patients with endometriosis in our cohort showed different gene expression profiles, represented by typically elevated gene expression of KRT18, NANOG, and VIM or of KRT19 and ESR1." (PMID 31717910, 2019). "We observed a higher NANOG and OCT4 mRNA levels in the SSEA1+ cell fraction isolated from women with endometriosis, possibly suggesting that they are at an earlier stage of differentiation than those from women without endometriosis." (PMID 30496412, 2019). "In this study, we analyzed the mRNA expression of REX-1 stemness gene and reconsidered three other stemness genes SOX-2, NANOG, OCT-4 in women with endometriosis compared to normal endometrium." (PMID 31417979, 2018). "In the endometriosis group, SOX2 and NANOG mRNA and protein expression were significantly increased in ectopic endometrium compared with eutopic endometrium; there was a trend towards lower OCT4 mRNA expression and higher OCT4 protein expression in ectopic endometrium." (PMID 24884521, 2014). "The mean relative expressions of OCT-4, NANOG, and SOX-2 were significantly higher in ectopic endometrium compared with eutopic and normal endometrium (p = 0.041), but the REX-1 mRNA increase was not significant between endometriosis and control groups." (PMID 31417979, 2018). "The transcription levels of OCT-4, NANOG, and SOX-2 mRNA were significantly increased in ectopic lesions compared with eutopic and control group (p = 0.041, p = 0.035, p = 0.048), although the REX-1 mRNA increase was not significant between endometriosis and control groups." (PMID 31417979, 2018).
leukemia (8 papers, 2016 to 2025). A malignant (clonal) hematologic disorder, involving hematopoietic stem cells and characterized by the presence of primitive or atypical myeloid or lymphoid cells in the bone marrow and the blood. "Correspondingly, the transcript-level expressions of stem cell-associated genes, including OCT4, KLF4, BMI1, NANOG and SOX2, were significantly increased in leukemia cells upon treatment with exosomes from BM-MSCs." (PMID 33789743, 2021). "The IGF2/IGF1R/NANOG signaling pathway has important functions in leukemia stem cell proliferation, and the knockdown of NANOG induces cell cycle arrest and apoptosis." (PMID 33336042, 2020). "NANOG has been reported in number of malignancies including leukemia." (PMID 35230971, 2022). "VENTX and NANOG are highly expressed in CD34+ leukemic stem cells (LSC, a subpopulation responsible for drug resistance, metastasis, and leukemia relapse) and their depletion blocks AML proliferation and growth." (PMID 35892595, 2022). "The inflammation-conditioned medium (inflamed-CM) generated by lipopolysaccharide-stimulated U937 human leukemia cells significantly increased the mRNA and protein levels of OCT4/NANOG preferentially in HBV-active (HBV+HBsAg+) HCC cells." (PMID 26919045, 2016). "Interestingly, VENTX and NANOG share activity in hematopoiesis by repressing the genes responsible for terminal differentiation (e.g., TAL1, KLF1), as well as promoting leukemia." (PMID 35892595, 2022).
renal carcinoma (7 papers, 2011 to 2022). A carcinoma arising from the epithelium of the renal parenchyma or the renal pelvis. "More importantly, the coexpression of OCT4 and NANOG in renal cancer was significantly associated with RCC subtypes, tumor size, and MVI in our study." (PMID 30082842, 2018). "Coexpression of OCT4 and NANOG in renal cancer was significantly associated with RCC subtypes." (PMID 30082842, 2018). "Our findings further suggest that OCT4 and NANOG coexpression may be valuable biomarkers in predicting the outcome of patients with renal cancer, especially in the ccRCC subtype." (PMID 30082842, 2018). "Cytoplasmic expression of NANOG could be considered as a novel independent prognostic predictor in patients with renal cancer." (PMID 30082842, 2018). "We have also found that MYBBP1A knock down increases the expression of CD34, NANOG and CXCR4, which are target genes of c-MYB, exclusively in renal carcinoma cell lines that express high levels of c-MYB." (PMID 30781655, 2019). "Interestingly, no significant change was observed in the expression of HES1, GLI1 and NANOG, whereas the expression of CTNNB1 was markedly increased, suggesting that CTNNB1 may be involved in increased renal cancer stem-like phenotype caused by the down-expression of PIK3R1." (PMID 25757764, 2015). "NANOG, SOX2, and OCT4 (octamer‐binding transcription factor 4) are key regulators of pluripotency and tumor invasion, and they have been proposed as biomarkers for cancer stemness in breast and renal carcinoma." (PMID 34532864, 2021). "Core pluripotency stem cell master regulators (OCT4, SOX2 and NANOG) along with epithelial–mesenchymal transition (EMT) markers (Snail, Slug, vimentin and N-cadherin) were induced in human prostate, breast, lung, bladder, colorectal, and renal cancer cells." (PMID 30742096, 2019). "Especially, the expression of c-MYC, KLF4, OCT4, NANOG and SOX2 implies that these 5 factors are involved in carcinogenesis and progression of RCC, and probably there are RCC cancer stem cells existing in renal carcinoma." (PMID 21982273, 2011). "To investigate if these master regulators could act as a core signature for clinically aggressive cancers, we explored an OCT4/SOX2/NANOG (OSN) expression signature in a large cohort of clinical cancers (n = 884), comprising of prostate (n = 275), bladder (n = 292) and renal cancers (n = 317)." (PMID 30742096, 2019). "However, the prognostic significance of OCT4 and NANOG is not clearly defined in renal cancers." (PMID 30082842, 2018). "First, OCT4 and NANOG are not specific biomarkers for RCC or they do not play dominant roles in the tumorigeness of RCC, but according to Bussolati's report, OCT4 and NANOG are expressed in tumor-initiating CD105+ stem cells in human renal carcinomas." (PMID 21982273, 2011).